PTK2B (protein tyrosine kinase 2 beta)
Diseases named in the same sentence as PTK2B in open-access papers (continued):
Sharing a sentence is not in itself a finding about the gene and the disease.
osteoporosis (7 papers, 2014 to 2023). A condition of reduced bone mass, with decreased cortical thickness and a decrease in the number and size of the trabeculae of cancellous bone (but normal chemical composition), resulting in increased fracture incidence. "Of these, SRC was the most highly associated and was shown to bind to PTK2B/PYK2 to provide energy for anti-osteoporosis drugs and to prevent the inhibitory effect of calcitonin by activating mitochondrial cytochrome C oxidase." (PMID 35051095, 2021). "As genetic variants in PTK2B increase the risk of osteoporosis and AD, Pyk2 pathway may be eligible for horizontal pleiotropy and suggest novel diagnostic and treatment biomarkers for AD." (PMID 33568650, 2021). "The genetic variants in protein tyrosine kinase 2β (PTK2B) are significantly associated with AD, body mass index, BMD, and Takayasu arteritis suggesting that Pyk2 pathway could be a converging pathway of the genetic correlation between osteoporosis and AD." (PMID 33568650, 2021).
Sepsis (7 papers, 2014 to 2025). Sepsis is defined as life-threatening organ dysfunction caused by a dysregulated host response to infection. "PTK2B exhibited the strongest binding affinity for esculin, a compound with therapeutic potential in sepsis." (PMID 40761792, 2025). "For instance, MLCK is implicated in phosphorylating a proline-rich protein tyrosine kinase 2 (PYK2/PTK2B) or focal adhesion kinase 2 (FAK2) that is involved in promoting lung vascular endothelial cell permeability during sepsis." (PMID 25072053, 2014).
cognitive deficits (6 papers, 2013 to 2025). "Sequestration of PTK2B transcripts to SGs and Ca2+ dyshomeostasis may synergistically affect synaptic loss, cognitive deficits induced by Aβ, and AD development." (PMID 37219408, 2023). "Thus, a variation that attenuates the activity of either NRG1 or PTK2B (human orthologs of Nrg1 and Pyk2) is likely to enhance the cognitive deficits caused by DAO protein." (PMID 23555897, 2013). "Ptk2b/Pyk2 modulates hippocampal excitatory synaptic transmission and contributes to cognitive deficits." (PMID 34200797, 2021).
Hypertension (6 papers, 2014 to 2025). The presence of chronic increased pressure in the systemic arterial system. "PTK2B has been implicated in cell growth, inflammatory responses, and vascular contraction, and has been associated with hypertension." (PMID 40857258, 2025). "PTK2B is involved in cell growth, inflammatory response, and osmotic pressure regulation after activation and mutated PTK2B is statistically associated with hypertension in Japanese population." (PMID 36911092, 2023). "Recent studies have linked the function of both PTK2B and NEDD9 to vascular integrity, angiogenesis, and hypertension." (PMID 25594051, 2014).
neuroblastoma (6 papers, 2015 to 2023). Neuroblastoma (NB) is the most common solid, extracranial childhood tumor. "ApoE4 and PTK2B have been previously linked mechanistically to Aß production by ApoE4 stimulated neuroblastoma cells." (PMID 26202100, 2015).
tauopathy (6 papers, 2021 to 2024). Neurodegenerative disorders involving deposition of abnormal tau protein isoforms (tau proteins) in neurons and glial cells in the brain. "Here, PTK2B, a risk factor for LOAD established through both GWAS and transcriptomic studies, was strongly prioritized and directly correlated with vulnerability to tauopathy." (PMID 36972319, 2023).
acute lymphoblastic leukemia (5 papers, 2019 to 2024). Leukemia with an acute onset, characterized by the presence of lymphoblasts in the bone marrow and the peripheral blood. "Acute lymphoblastic leukemia (ALL) contains multiple activated kinase and cytokine receptor signatures, such as genomic alterations in PTK2B." (PMID 36291283, 2022).
Cerebral ischemia (5 papers, 2014 to 2021). Restriction of arterial blood supply to the brain associated with insufficient oxygenation to support the metabolic requirements of the tissue. "At 24-72 h after focal cerebral ischemia, phospho-Ptk2b was rapidly induced in microglia surrounding the necrotic infarction area, and phospho-Ptk2b was confirmed to colocalise with phospho-p38 and act as an upstream mediator of the p38 signalling pathway after cerebral ischemia." (PMID 29348887, 2017).
Huntington disease (5 papers, 2017 to 2022). Huntington disease (HD) is a rare neurodegenerative disorder of the central nervous system characterized by unwanted choreatic movements, behavioral and psychiatric disturbances and dementia. "For instance, dendrites on pyramidal CA1 hippocampal neurons of Ptk2b−/− mice suffer a loss of dendritic spines and PSD-95 clusters; moreover, Pyk2 restoration in the hippocampi of Huntington’s disease model mice, which exhibit low Pyk2, partially rescues this same phenotype." (PMID 34943950, 2021).
liver cancer (5 papers, 2007 to 2023). An epithelial or non-epithelial malignant neoplasm that arises from the liver. "In liver cancer, PTK2B expression is associated with tumor invasion behavior and poor prognosis." (PMID 37622116, 2023).
Anxiety (4 papers, 2012 to 2019). Intense feelings of nervousness, tension, or panic often arise in response to interpersonal stresses. "These genes may still be interesting candidate genes, when looking at monoamine availability (PCLO), or more specific (endo-)phenotypes like cortisol levels (ANPEP) and co-morbid anxiety (PTK2B and GZMK)." (PMID 22649524, 2012).
dementia (4 papers, 2014 to 2025). Loss of intellectual abilities interfering with an individual's social and occupational functions. "Also, we aimed to investigate the association of candidate loci with the age at the onset of AD and confirmed that the candidate genes including HLA-DRB1, CD2AP, and PTK2B may contribute to the development of early onset dementia." (PMID 32116649, 2020).
endometriosis (4 papers, 2022 to 2026). The growth of functional endometrial tissue in anatomic sites outside the uterine body. "We identified a non-receptor tyrosine kinase, proline-rich tyrosine kinase 2 (PYK2 or PTK2B), and examined the expression of PYK2 in endometriosis." (PMID 40289074, 2025). "In hESC cells co-cultured with gestational epithelial endometriosis organoids, SFRP1, CDC42, RAC1, and WASF3 were upregulated, while PTK2B was downregulated, reflecting the miRNA cargo of ENDO-GEST-derived EVs." (PMID 42282918, 2026).
epilepsy (4 papers, 2021 to 2026). A brain disorder characterized by episodes of abnormally increased neuronal discharge resulting in transient episodes of sensory or motor neurological dysfunction, or psychic dysfunction. "Case 1085: Splicing and expression analysis identified the PTK2B gene as a candidate gene due to an intron retention event in intron 27 in a male with features of autism, behavioral issues, obesity, epilepsy and growth hormone deficiency." (PMID 40593860, 2025). "There were 8 proteins shared between epilepsy and ischemic stroke: SH3BGRL3, BPNT1, PTPMT1, PACSIN3, MIPEP, CMC2, ABCA5, and PTK2B." (PMID 40624693, 2025).
viral infection (4 papers, 2022 to 2025). "To further explore the role of PTK2B in host defense against viral infection, we isolated primary MEFs from Ptk2b-deficient and littermate control embryos by crossing Ptk2b heterozygous mice." (PMID 37989995, 2023). "To investigate the role of PTK2B in immune defense against viral infection in vivo, we intravenously infected Ptk2b-deficient and control mice with HSV-1." (PMID 37989995, 2023). "Functional assays reveal that PTK2B depletion reduces antiviral signaling in mouse embryonic fibroblasts, macrophages and dendritic cells, and genetic experiments show that Ptk2b-deficient mice are more susceptible to viral infection than control mice." (PMID 37989995, 2023). "Given that PTK2B is highly expressed in immune cells, our findings suggest that PTK2B played an important role in activating sufficient immune responses to virus infection to ensure the efficient elimination of viruses." (PMID 37989995, 2023). "Collectively, these results suggest that PTK2B plays a critical role in immune defense against viral infection in vivo." (PMID 37989995, 2023). "Together, the findings suggest that PTK2B mediates innate immune responses to viral infection by regulating the STING-TBK1 signaling." (PMID 37989995, 2023). "Next, we examined the effect of PTK2B in regulating TBK1 activation during viral infection." (PMID 37989995, 2023). "Thus, our findings uncover a mechanism by which the PTK2B oligomerization induced by viral infection plays a positive role in regulating antiviral signaling by promoting TBK1 phosphorylation and oligomerization." (PMID 37989995, 2023). "Given that PTK2B and TBK1 could co-localize together and form cellular granules upon HSV-1 infection, we reasoned that PTK2B could potentially undergo oligomerization, in response to virus infection." (PMID 37989995, 2023). "We found that the MG132 treatment also failed to increase the association of PTK2B with STING upon virus infection, suggesting that virus infection has no apparent effect on the PTK2B-STING association." (PMID 37989995, 2023). "In the absence of viral infection, no apparent green signal was detected in cells with co-expression of PTK2B-GA and PTK2B-GB." (PMID 37989995, 2023).
HIV-1 infection (3 papers, 2014 to 2025). The type species of lentivirus and the etiologic agent of acquired immunodeficiency syndrome (AIDS). "In contrast, a study investigating whether STKIs—including dasatinib—exerted their inhibitory effect on HIV-1 infection through the interaction between c-SRC and its ligand PTK2B concluded that multiple postentry steps played a major role in blocking HIV-1 infection." (PMID 31619990, 2019).
mastitis (3 papers, 2019 to 2025). Inflammation of breast tissue during lactation or postpartum due to an obstructed duct or infection. "We used two-stage correlation analysis to find 27 significant SNPs associated with risk of mastitis, among which three SNPs (rs75762330, rs88640083, and rs20438858) were annotated to immune-regulated genes (PTK2B, SYK, and TNFRSF21)." (PMID 31447828, 2019). "In bPBLs and bMECs, PTK2B, SYK, and TNFRSF21 are involved in different mechanisms of immune responses associated with mastitis." (PMID 31447828, 2019). "It showed that expression of SYK and PTK2B was down-regulated significantly (P < 0.001) in mastitis cows in comparison to the control group, while TNFRSF21 was up-regulated." (PMID 31447828, 2019). "Taken together, these results provided strong evidence for the study of SNPs in bovine mastitis, and revealed the role of SYK, PTK2B, and TNFRSF21 in bovine mastitis susceptibility/tolerance." (PMID 31447828, 2019). "Notably, PTK2B—a protein tyrosine kinase family member—showed significant downregulation, consistent with its established regulatory role in bovine mastitis pathogenesis." (PMID 41305370, 2025). "SYK and PTK2B may be involved in the SYK/PTK2B/AKT1/JAK2 pathway in bMECs that stimulates IL-8 secretion and recruits neutrophils to kill pathogenic microorganisms, resulting in the resistance to mastitis inflammation." (PMID 31447828, 2019). "PTK2B expression levels in bPBLs of mastitis cows were significantly down-regulated (P < 0.001) and had a time course difference in LPS-stimulated bEMCs, suggesting that PTK2B plays an important role in clinical mastitis." (PMID 31447828, 2019). "The LD block data also showed that there were strong LD relationship between rs75762330 and PTK2B, rs88640083 and SYK, rs20438858 and TNFRSF21, suggesting that these three immune-regulated genes are important candidate genes associated with mastitis traits in Chinese Holstein cows." (PMID 31447828, 2019). "Transcriptional analysis showed that PTK2B and SYK expression level was down-regulated in both bPBLs of clinical mastitis cows and in vitro LPS (E. coli)–stimulated bMECs indicating that PTK2B and SYK are important candidate genes associated with mastitis resistance traits." (PMID 31447828, 2019). "These included genes and QTLs related to somatic cell count and mastitis (CACNA2D1, SEMA5A, NEGR1, PTK2B, CTNNA3), gastrointestinal parasites (PTK2B), and various viral or bacterial diseases." (PMID 41273432, 2025). "The temporal sequences of SYK, PTK2B, TLR4, and IL-1β expression are similar, suggesting that there might be an immune response pathway in bMECs participating in bovine mastitis inflammatory response." (PMID 31447828, 2019). "Importantly, PTK2B and SYK expression was down-regulated in both peripheral blood leukocytes (PBLs) of clinical mastitis cows and in vitro LPS (E. coli)–stimulated bovine mammary epithelial cells, while TNFRSF21 was up-regulated." (PMID 31447828, 2019). "Therefore, up-regulation of IL-10 expression in bPBLs, suggesting that IL-10 may be regulated by PTK2B and SYK, and thus participate in the regulation of inflammatory response in dairy cow mastitis." (PMID 31447828, 2019).
Obesity (3 papers, 2021 to 2025). Accumulation of substantial excess body fat. "In line with this hypothesis, genes PTK2B, KANSL1 and ADAM10 have been previously associated with obesity and BMI, while ABCA7 and ADAM10 have been associated with blood pressure." (PMID 34992629, 2021).
Parkinson disease (3 papers, 2021 to 2024). A progressive degenerative disorder of the central nervous system characterized by loss of dopamine producing neurons in the substantia nigra and the presence of Lewy bodies in the substantia nigra and locus coeruleus. "Variants in the BIN1 gene (p.Asn232Lys, and c.1462-3C > T) were linked to myopathy, while the variant in PTK2B was associated with Parkinson’s disease." (PMID 36133075, 2022). "The DisGeNET database labels NLRP1, MSC, PTK2B, TAC1 and FOSL2 as genes associated with Parkinson’s disease, with association scores of 0.964, 0.944, 0.907, 0.889 and 0.888, respectively." (PMID 38350848, 2024).
cervical cancer (2 papers, 2019). A primary or metastatic malignant neoplasm involving the cervix. "The protein tyrosine kinase PTK2B involved in Ca2+-induced regulation of ion channel and MAP kinase activation, which has underlying relationship with cervical cancer." (PMID 31133010, 2019). "CRKL depletion significantly alters the retention of variable introns of PTK2B and TSC2, and the inclusion of variable exons of MELK, and these tumorigenesis involving genes might then affect development or progression of cervical carcinoma." (PMID 31133010, 2019).
COVID-19 (2 papers, 2022 to 2024). A disease caused by infection with severe acute respiratory syndrome coronavirus 2. "Specifically, we identified three markers, apolipoprotein E (APOE), membrane-spanning 4-domain subfamily A member 4A (MS4A4A), and protein-tyrosine kinase 2-beta (PTK2B), which displayed the same trend in AD and COVID-19 compared to the control group according to our AD-high-risk scores." (PMID 36211330, 2022).
dental caries (2 papers, 2012 to 2013). The decay of a tooth, in which it becomes softened, discolored, and/or porous. "For example, two genes PTK2B and RHOU were suggested to be candidate loci previously, and they are involved in pathways that have been implicated to dental caries." (PMID 24146904, 2013). "In general, we identified several suggestive loci (P-value ≤ 10E-05) within or near genes with plausible biological roles for dental caries, including RPS6KA2 and PTK2B, involved in p38-depenedent MAPK signaling, and RHOU and FZD1, involved in the Wnt signaling cascade." (PMID 23259602, 2012).
heart failure (2 papers, 2020 to 2024). Inability of the heart to pump blood at an adequate rate to meet tissue metabolic requirements. "Notably, inhibition of PTK2B has been proven to improve cardiac function in rat models with heart failure and post-AMI ventricular remodeling." (PMID 38956669, 2024).
sarcopenia (2 papers, 2025). Progressive decline in muscle mass due to aging which results in decreased functional capacity of muscles. "Using the MTA‐MO method, we identified 639 gene targets, and by analysing PPIs and querying public databases, we narrowed this list down to seven potential hub genes associated with sarcopenia (ESR1, ATM, CDC42, EP300, PIK3CA, EGF and PTK2B)." (PMID 40045692, 2025). "In silico analysis of 1940 drug candidates identified canagliflozin as a promising candidate for repurposing in sarcopenia, demonstrating the strongest binding affinity to the PTK2B protein (inhibition constant 6.97 μM)." (PMID 40045692, 2025). "Applying MTA-MO to multi-omics data identified seven potential hub genes associated with sarcopenia: ESR1, ATM, CDC42, EP300, PIK3CA, EGF, and PTK2B." (PMID 41303670, 2025).
schizophrenia (2 papers, 2013 to 2018). A major psychotic disorder characterized by abnormalities in the perception or expression of reality. "As described in the introduction, the polymorphisms of NRG1 and PTK2B are associated with schizophrenia, respectively." (PMID 23555897, 2013). "Using candidate-gene positional cloning approach we have finely mapped genes vulnerable to schizophrenia in Taiwan, including DISC1 at chromosome 1q42, RASD2 and CACNG2 at chromosome 22q12, and DPYSL2, TRIM35 and PTK2B at chromosome 8p21 (in preparation)." (PMID 23555897, 2013).
schwannoma (2 papers, 2018 to 2021). A benign, usually encapsulated slow growing tumor composed of Schwann cells. "PTK2B (inhibitor: defactinib) was upregulated in merlin-deficient schwannoma cells by Panobinostat and AURKA (inhibitor: alisertib) was upregulated in merlin-deficient meningioma upon treatment with GSK2126458 and CUDC-907." (PMID 29897904, 2018). "In the human schwannoma model (HS01 and HS11), PTK2 and PTK2B (FAK1 and FAK2) were induced by all three drugs in a merlin-deficient-specific manner." (PMID 29897904, 2018). "Collectively, these data identify brigatinib as a direct and potent inhibitor of multiple kinases, including FAK1 (PTK2) and FAK2 (PTK2B), and novel targets, GAK and TNK2, in both arachnoid and schwannoma cells." (PMID 34264955, 2021).
ulcerative colitis (2 papers, 2021 to 2024). An inflammatory bowel disease involving the mucosal surface of the large intestine and rectum. "Among the downregulated DEGs of GA that were enriched for this pathway, PTK2B was significantly upregulated in the inflamed mucosa of patients with ulcerative colitis." (PMID 38540020, 2024).
amyloid (1 paper, 2025). "Deletion of Ptk2b in APP/PS1 transgenic mice rescued synaptic loss and memory deficits, whereas overexpression rescued behavior and increased amyloid plaque number in 5xFAD mice." (PMID 40026671, 2025).
coeliac disease (1 paper, 2008). "Moreover, protein tyrosine kinase 2 beta (PTK2B), which enhances apoptosis was found to be down-regulated in active coeliac disease." (PMID 18691394, 2008).
Glucose intolerance (1 paper, 2022). Glucose intolerance (GI) can be defined as dysglycemia that comprises both prediabetes and diabetes. "In mouse studies, protein tyrosine kinase 2 beta (PTK2B) was found to play a critical role in the differentiation of beige adipocytes, CD47–/– knockout resulted in resistance to insulin desensitisation, glucose intolerance and diet-associated weight gain." (PMID 36151087, 2022).
hyperlipidemia (1 paper, 2025). "In this study, HCK, LYN, WAS, and PTK2B were identified as hub genes using Maximal Clique Centrality, holding significant implications for future research on hyperlipidemia." (PMID 41446394, 2025).
ischemic cardiomyopathy (1 paper, 2025). Ischemic cardiomyopathy is a cardiomyopathy in which a weakness in the muscle of the heart due to inadequate oxygen delivery to the myocardium with coronary artery disease being the most common cause. "Additionally, PTK2B expression has been linked to ischemic cardiomyopathy." (PMID 40857258, 2025).